HTR3A (5-hydroxytryptamine receptor 3A)
Diseases named in the same sentence as HTR3A in open-access papers (continued):
Sharing a sentence is not in itself a finding about the gene and the disease.
autism (1 paper, 2021). Persistent deficits in social interaction and communication and interaction as well as a markedly restricted repertoire of activity and interest as well as repetitive patterns of behavior. "Mutations in serotonin pathway genes, especially the serotonergic receptor subunit gene HTR3A, are associated with autism." (PMID 34646371, 2021). "The hippocampus in human brain is crucial for memory 36, associated with autism 37, 38 and EP 39, suggesting that it may play an essential role in the behavioral phenotypes of the Htr3a-/- mice." (PMID 34646371, 2021). "However, the association of HTR3A deficiency with autism and the underlying mechanisms remain unknown." (PMID 34646371, 2021). "Taken together, the Htr3a KO mice exhibited autistic-like behaviors, impaired learning/memory and attenuated PTZ-induced seizures, suggesting that HTR3A as a potential causal gene of autism." (PMID 34646371, 2021).
carpal tunnel syndrome (1 paper, 2026). Entrapment of the median nerve in the wrist that is characterized by numbness, tingling and painful movement. "These included associations with genes involved in neurotransmitter signaling (HTR3A), immune function (HLA-DQB1, BCL11A), extracellular matrix remodeling (COL11A1, ADAMTS17, LOXL4), axon guidance and neural development (DCC, ETV1, NEGR1), and carpal tunnel syndrome (DIRC3)." (PMID 41518141, 2026).
cholangiocarcinoma (1 paper, 2024). A carcinoma that arises from the intrahepatic biliary tree (intrahepatic cholangiocarcinoma) or from the junction, or adjacent to the junction, of the right and left hepatic ducts (hilar cholangiocarcinoma). "TCGA-CHOL (Cholangiocarcinoma) shows upregulations of HTR3A (35.1-fold) and GPR35 (G Protein-Coupled Receptor 35) (33.9-fold), with downregulations in ADRA1A (−74.3-fold) and ESR1 (Estrogen Receptor 1) (−43.2-fold)." (PMID 39766077, 2024).
glioblastoma (1 paper, 2024). The most malignant astrocytic tumor (WHO grade IV). "Knockdown of nine PTGs significantly decreased cell viability, of which lower expression levels of DRD1, DRD2, HTR3A and TACR1 were also associated with better patient survival in The Cancer Genome Atlas (TCGA) glioblastoma cohort." (PMID 39304781, 2024).
Glucose intolerance (1 paper, 2024). Glucose intolerance (GI) can be defined as dysglycemia that comprises both prediabetes and diabetes. "Also, glucose intolerance appeared in Htr3a knockout mice during pregnancy, and insulin secretion was increased in pancreatic islets by treatment with an Htr3 agonist and decreased by an Htr3 antagonist." (PMID 38999937, 2024).
nicotine addiction (1 paper, 2022). "The results found in Chinese Han smokers further indicate the interaction of HTR3A and HTR3B genes in nicotine addiction." (PMID 35457612, 2022).
stomach cancer (1 paper, 2024). "Research has identified serotonin receptors, specifically HTR2A, HTR2B, HTR3A, and HTR7, as potential targets for both the prevention and treatment of stomach cancer." (PMID 39766808, 2024).
cancer (21 papers, 1999 to 2025). A tumor composed of atypical neoplastic, often pleomorphic cells that invade other tissues. "In oesophageal squamous carcinoma, LINC01305 was found to regulate HTR3A mRNA, thereby promoting cancer cell metastasis and proliferation." (PMID 36384476, 2022). "Several recent papers have discussed the effects of HTR3A on tumor cells, which plays a role in tumor progression in specific types of cancer." (PMID 35757399, 2022). "Studies have shown that SNPs in HTR3A and HTR3B encoding subunits of the 5-HT3-receptor are associated with impaired receptor function and nausea in adult cancer patients." (PMID 33794950, 2021). "In addition, several MMRs appear to have a distinct behavior in different cancer types, like CNR1, which is statistically significantly downregulated in 10 cancer types and upregulated in five, while HTR3A does the opposite." (PMID 39766077, 2024). "Furthermore, HTR3A is targeted by several FDA approved cancer drugs retrieved from PiHelper, an open source compilation of drug-target and antibody-target associations derived from several public data sources." (PMID 30255801, 2018). "Other molecules, such as CP, CERLD2, CTSD, HSPA5, HTR3A and TUBB2C, are also frequently up-regulated in cancer." (PMID 28056051, 2017). "Finally, except for HTR3A, sensitivity of cancer cell lines to CWHM-974 and FLU did not correlate with mRNA expression of dopamine and serotonin receptors suggesting that these effects are independent of dopamine or serotonin receptor activity." (PMID 37909019, 2023).
tumor (5 papers, 2022 to 2025). "Our study contributes novel insights into the interactions between tumor cells and infiltrating immune cells, confirming that HTR3A and NIPAL4 may be involved in BRAF-mutated PTC by interfering with immune cells." (PMID 35757399, 2022). "We initially examined the mRNA expression of multiple 5-HT receptors that have been confirmed to involve in tumor progression, and it was found that HTR3A was significantly overexpressed in the GC cells compared with GES-1 gastric epithelial cells." (PMID 38129926, 2023). "The present study confirmed that upregulation of HTR3A was associated with shorter PFS in BRAF-mutated PTC, supporting a tumor-promoting role of HTR3A and a potential role in predicting prognosis." (PMID 35757399, 2022). "Our work demonstrated that HTR3A and NIPAL4 expression were associated with prognosis and tumor-infiltrating immune cells." (PMID 35757399, 2022). "To investigate the possible role of HTR3A receptor in regulation of proliferation in tumor cells, we treated the cells with the HTR3A agonists, N-methylquipazine dimaleate (NMQ) and SR57277, as well as antagonists, VUF10166 and granisetron HCl, in the presence of 5HT." (PMID 35614045, 2022).
neurological diseases (3 papers, 2014 to 2022). "Among them, Nptx2, Nedd9, Rorb, Cux2, and Htr3a are involved in neuronal development or associated with neurological diseases." (PMID 25071448, 2014).
adenocarcinoma (1 paper, 2024). A common cancer characterized by the presence of malignant glandular cells. "In acinar LUAD, the expression of HTR3A and Ki‐67 is higher than that in lepidic adenocarcinoma." (PMID 38318637, 2024).
HTR3A also shares sentences with these, for which no sentence is quoted: psychiatric disorder (9 papers); migraine (8); cognitive deficits (5); colitis (5); ischemic colitis (4); epilepsy (3); Headache (3); Obesity (3); alcohol (2); Anorexia (2); colorectal cancer (2); diabetes (2); gastroesophageal reflux disease (2); Stroke (2); Ventricular arrhythmia (2); acne (1); Ascites (1); atopic dermatitis (1); attention deficit-hyperactivity disorder (1); Borderline personality disorder (1); brain infarction (1); central sleep apneas (1); cerebellar tremor (1); cerebral infarction (1); cholestasis (1); Chronic constipation (1); cognitive decline (1); colon cancer (1); COVID-19 (1); delirium (1).
A further 36 diseases each share a sentence with HTR3A in 1 paper.